RORA (RAR related orphan receptor A)
Diseases named in the same sentence as RORA in open-access papers (continued):
Sharing a sentence is not in itself a finding about the gene and the disease.
sleep disorder (1 paper, 2025). A change from the patient's baseline sleeping pattern, in the hours slept and/or an alteration/dysfunction in the stages of sleep. "Previous studies have primarily focused on CLOCK and PER2 in sleep disorders, but RORA’s role remains underexplored, particularly in mental worker populations." (PMID 40951374, 2025). "Correlation study of CLOCK, PER2, and RORA genes with sleep disorders." (PMID 40951374, 2025).
T-cell leukemia (1 paper, 2025). A malignant disease of the T-lymphocytes in the bone marrow, thymus, and/or blood. "SR1078 is an agonist of RORα/γ, which inhibited NF-κB function and enhanced CD8+ T-cell responses in the Jurkat T cell leukemia cell line." (PMID 40495887, 2025).
uveitis (1 paper, 2020). An inflammatory process affecting a part of or the entire uvea. "Finally, the upregulated gene Rorα regulating the Th17 cell differentiation and immune response may provide the evidence of the increased levels of the cytokine of IL-17 in the supernatant from enriched T cells in the offspring influenced by parental uveitis." (PMID 32612602, 2020).
vitamin A deficiency (1 paper, 2022). Deficiency of vitamin A due to malnutrition, malabsorption, or dietary lack. "Vitamin A deficiency reduced the level of RXRβ mRNA, changed the rhythm amplitude of the PER1, REV-ERB genes and REV-ERB protein, and phase-shifted the daily peaks of RORα protein as well as BMAL1, RORα, RC3 and BDNF mRNA levels." (PMID 36466383, 2022).
tumor (94 papers, 2007 to 2025). "Downregulation and reduced activation of RORα have been implicated in tumor development and progression, establishing it as a recognized tumor suppressor." (PMID 41425709, 2025). "Further analysis explored RORA’s enriched pathways and its relationship with immune response, tumor mutation burden, and drug sensitivity." (PMID 40638694, 2025). "For instance, RORA expression is reduced in colorectal cancer tissues, and its low expression is associated with increased tumor invasiveness and poor prognosis." (PMID 40638694, 2025). "GC patients with low RORα expression were not only associated with high circulating tumor cells (CTC) and high vascular endothelial growth factor (VEGF) levels." (PMID 38184549, 2024). "The authors of the study showed that EZH2 was able to monomethylate RORa, causing a degradation of the protein through the ubiquitin–proteasome pathway, thereby inhibiting its tumor suppressive role." (PMID 39769907, 2024). "Lower levels of RORα and RORγ are associated with more aggressive tumor phenotypes and poorer prognoses, whereas elevated expression correlates with improved survival outcomes." (PMID 39518891, 2024). "We showed that downregulation of RORα is associated with poor clinical outcomes and that reduced RORα expression promotes tumor growth and cancer cell invasion." (PMID 35605663, 2022). "RORA expression was found to be significantly associated with death, tumor stage, and metastasis of LUAD." (PMID 35504868, 2022). "Functional analyses have shown that abnormal RORα expression is associated with many diseases and tumor development." (PMID 33336001, 2020). "Low expression of RORα protein was significantly associated with tumor size, tumor differentiation, T stage, TNM stage, and lymph node metastasis." (PMID 28052040, 2017). "In turn this causes the loss of tumour suppressor activity of RORα, which ultimately leads to the development of more aggressive tumours." (PMID 25949794, 2014). "Conversely, in other cancer types, low RORA expression may be linked to tumor growth and metastasis." (PMID 40638694, 2025). "In the present study, we identified a specific N-terminal domain (NTD) of RORα1 that potentiated the downregulation of target genes involved in tumor progression and proliferation, based on results from RORα-deficient mouse embryonic fibroblasts and prostate carcinoma tissues." (PMID 30987323, 2019). "Furthermore, in contrast to mice transplanted with WT BM, we unexpectedly detected the formation of metastases from the primary TC1 tumours in ILC2-deficient mice transplanted with RORα−/− BM." (PMID 29440650, 2018). "RORα-deficient mice would also have reduced IL-13 production due to the absence of ILC2s but it is not known whether this has also contributed to the increase in tumour burden." (PMID 33535624, 2021). "Similar decreases in RORA expression were observed in GC tumor tissues compared to adjacent non-tumor tissues." (PMID 40638694, 2025). "Low expression of RORα leads to high circulating tumor cell count and up-regulation of VEGF in GC, while silencing RORα can significantly promote the proliferation, up-regulate N-cadherin and Vimentin, and down-regulate E-cadherin." (PMID 41425709, 2025). "A number of studies have shown that RORα expression is significantly decreased during tumor development and progression, and that exogenous RORα expression represses cell proliferation and tumor growth." (PMID 41465212, 2025). "Our analysis revealed that RORA expression is lower in tumor samples compared to normal samples, and single-cell analysis showed significant upregulation of RORA in CD8 + T cells." (PMID 40638694, 2025). "Although RORα is inhibited in cSCC, its activation has been demonstrated to inhibit tumor growth, highlighting its potential as a promising target for future cSCC treatments." (PMID 39518891, 2024).
tumor (continued). "In comparing RORα-/- to wild-type controls, we have observed increased spread of circulating tumour cells and formation of metastases in distal organs." (PMID 38172434, 2024). "Our work also documented that the presence of ILC2s significantly inhibits tumour formation in wild-type chimeric mice bearing tumours expressing IL-33 when compared to RORα-/- chimeras, which lack ILC2s." (PMID 38172434, 2024). "This reduction was partially rescued when the RORA gene was silenced, indicating that RORA gene expression is epigenetically regulated by hsa-miR-20a-5p, thus reducing the proliferative capacity of tumour cells." (PMID 39010137, 2024). "RORα has been reported as a potential tumor suppressor, and its expression is downregulated in almost all solid tumors." (PMID 38791992, 2024). "In GBM, RORα reduced tumour-promoting inflammation by downregulation of the JAK2 (Janus Kinase 2)/STAT3 (Signal Transducer And Activator Of Transcription 3) /IL-6 (Interleukin 6) and the TNF-α/NF-κB pathway." (PMID 38378853, 2024). "Retinoid-related orphan receptor alpha (RORα), a member of the orphan nuclear factor family, is considered a potential tumor suppressor." (PMID 38791992, 2024). "Retinoic acid receptor-related orphan receptor alpha (RORα), a candidate tumor suppressor, is prevalently downregulated or lost in malignant breast cancer cells." (PMID 38791992, 2024). "RORα was associated with the inhibition of MDSC differentiation and function, and the suppression of tumour-promoting cytokine secretion." (PMID 38378853, 2024). "In contrast, some genes such as SLC2A3 and RORA are highly expressed in other cells except tumor cells." (PMID 37496994, 2023). "CircGSK3B is able to directly interact with EZH2, suppressing the deposition of H3K27me3 on the RORA promoter, which can upregulate RORA and eventually inhibit tumor growth, invasion, and metastasis." (PMID 36750826, 2023). "Taken together, these findings indicate that TET2 inhibits tumour cell growth and metastasis by activating demethylation activity via regulation of RORA-SPARC expression." (PMID 37620362, 2023). "In our study, we identified a new canonical mechanism of RORα-mediated tumour suppression by which the transcription of the ubiquitinase NEDD4 is activated, leading to c-myc degradation." (PMID 36316442, 2022). "Tumour growth was significantly accelerated in RORα/γ-silenced cells and slowed in RORα/γ-overexpressing cells." (PMID 36316442, 2022). "TIMELESS was significantly upregulated (P < 0.05) while RORA was significantly downregulated (P < 0.0001) in tumor tissue compared to the adjacent normal tissue." (PMID 35078435, 2022). "More importantly, AOM/DSS T cells highly expressed Id2 downstream of TGFβ signaling, which has been shown to lead to RORα-dependent tumor-promoting inflammation, evident in this population by high Rora and Il17a expression." (PMID 35600339, 2022). "RORα has been identified as a potential tumor suppressor; however, how downregulation of RORα promotes cancer progression is not fully understood." (PMID 35605663, 2022). "Collectively, circGSK3B directly interacts with EZH2 to block the binding of EZH2 to the RORA promoter, leading to an increase in RORA expression and the suppression of tumor progression through Wnt signaling pathway regulation." (PMID 34666800, 2021). "Quantified data from FACS analysis showed that RORα expression significantly reduced the number of total macrophages in 4T1 tumor tissues; interestingly, the portion of M1-like macrophages was increased upon RORα expression." (PMID 34639006, 2021). "Tumors in mice treated with Rorα agonist were significantly smaller than those of control mice (mean tumor volume: 86.82 vs. 204.77 mm3; p < 0.05)." (PMID 33664254, 2021).
tumor (continued). "Overall, Rorα is a critical regulator of tumor growth in cSCC, and the activation of Rorα can inhibit its growth." (PMID 33664254, 2021). "We, therefore, examined the in vivo anti-tumor activity of restoring RORα function via SR1078 and genetic overexpression." (PMID 34183658, 2021). "Overall, our results demonstrated that restoration of the molecular clock via activation of RORα blocks MYCN-driven tumor growth and lipid metabolism." (PMID 34183658, 2021). "Overexpression of RORα significantly blocked tumor growth (p = 0.013), and DOX-induced tumors also showed higher BMAL1 protein levels." (PMID 34183658, 2021). "The data suggested that circRELN downregulation governed the miR-1290/RORA axis to inhibit tumor growth in vivo." (PMID 34479497, 2021). "Immunohistochemistry analysis showed that F4/80 positive cells were reduced in RORα-expressing 4T1 tumor sections." (PMID 34639006, 2021). "The recruitment of RORA can induce the expression of the tumor suppressor genes F-box/WD repeat-containing protein 7 (FBXW7), Semaphorin 3F (SEMA3F), and P21, leading to apoptosis and suppression of tumor cell proliferation." (PMID 34285836, 2021). "Collectively, these results indicate that the Rorα expressing IL-7R-positive immune cells limit CRC progression, as their loss augments tumour growth." (PMID 33535624, 2021). "This led to an elevation in RORA expression and the suppression of tumor progression, revealing the critical roles of circGSK3B and EZH2 in GC progression." (PMID 34666800, 2021). "Previous studies have shown downregulations of RORA expression in various tumor tissues, such as breast, lung, prostate, and colorectal cancer." (PMID 34408982, 2021). "Consistent with previous results, RORα was found to be upregulated in tumor tissues and its suppression inhibited cell growth in GC cells." (PMID 33336001, 2020). "RORα can regulate the expression of some tumor related genes (such as nm23 and N-Myc) and can also inhibit tumor development by inhibiting the Wnt/β-catenin signaling transduction pathway." (PMID 33336001, 2020). "In summary, decreases in VDR, RORγ, and RORα expression correlated with an unfavorable outcome for OC, and compounds targeting these receptors had a context-dependent anti-tumor activity in vitro." (PMID 33227893, 2020). "Our studies have broadened the spectrum of the action of RORα to the regulation of tumor progression and proliferation by an unanticipated cross-regulation with the Wnt/β-catenin pathway." (PMID 30987323, 2019). "Of the promoters gaining methylation in our sample, many have already been shown to have tumour suppressor activity, including RORa, FAN1, PRDM1, CYGB, L3MBTL4, EPB41L3, with ZNF471 and ZNF671 being specifically silenced by methylation." (PMID 31357948, 2019). "We observed that core clock genes, PERs, CRY2, CLOCK, NR1D2, RORA and RORB exhibited global patterns of somatic loss and downregulation across multiple tumour types." (PMID 31014368, 2019). "As an important transcriptional cofactor, RORα plays a crucial role in activating or inactivating some key tumor suppressor genes or oncogenes." (PMID 30293994, 2018). "RORA has recently been identified as a novel circadian rhythm gene which plays an important role in tumor suppression by inhibiting the cell proliferation." (PMID 30293994, 2018). "RORA maps to the middle of chromosome 15q22.2, a highly unstable region with frequent breaks in cancers, and acts as a tumor suppressor by inhibiting cancer proliferation, apoptosis and invasion." (PMID 30293994, 2018).
tumor (continued). "The frequency of ILC2s isolated from lymph nodes of mice transplanted with RORα−/− BM bearing IL-33-expressing tumours was less than 0.05% of total cells isolated, and further served as a control for the efficiency of bone marrow transplantation." (PMID 29440650, 2018). "RORα plays an important role in increasing apoptosis, which forms a basis for its tumor-suppressive regulatory role." (PMID 28052040, 2017). "The observation that Rorα mRNA level is often down-regulated in cancer cell lines and human cancer tissues support the potential tumor suppressive function of RORα." (PMID 28931919, 2017). "Mechanistically, AMPK reduction leads to the decreased activation and transcription of RORα, resulting in the expression of tumor suppresser genes." (PMID 28052040, 2017). "RORα and RORγ exhibit, inter alia, anti-tumor effects and disturbances in their functions and expression can contribute to a development and progression of malignant lesions." (PMID 27542227, 2016). "A number of studies reported that RORα expression is significantly down-regulated during tumor development and progression, while expression of exogenous RORα inhibited cell proliferation and tumor growth." (PMID 26878025, 2015). "On the other hand, reducing SEMA3F expression has little effect on tumor growth, suggesting that the tumor suppressor function of RORα involves other target genes and pathways as well." (PMID 23443091, 2012). "It is most likely that tumor suppressor function of RORα is mediated by multiple pathways and involves canonical and non-canonical nuclear receptor activity." (PMID 23443091, 2012). "Reactivation of RORα could significantly improves the anti-tumor activity of etoposide and serve as a therapeutic strategy for MYCN-amplified NBs by blocking the dysregulation of molecular clock and cell metabolism mediated by MYCN." (PMID 40166471, 2025). "Furthermore, RORA can modulate immune responses, enhancing the immune system’s ability to eliminate tumor cells." (PMID 40638694, 2025). "In contrast, RORA expression was notably reduced in tumor tissues." (PMID 40191195, 2025). "Additionally, immunohistochemical analysis from HPA showed that RORA expression was lower in tumor tissues compared to non-tumor tissues." (PMID 40638694, 2025). "Moreover, the subcutaneous tumor group of RORα-KO-MFC showed higher Ki-67 and PCNA expression levels than that of CON-MFC group in mice, while these phenomena were also reversed by SR1078." (PMID 38184549, 2024). "CLOCK/BMAL1 induces tumour promoting inflammation whereas RORα abrogates it." (PMID 38378853, 2024). "Moreover, The subcutaneous tumor group of glucose showed lower RORα expression levels than that of Vehicle group in mice." (PMID 38184549, 2024). "Consequently, a decrease in RORα levels fosters the increased viability of tumor cells which can be counteracted by AMPK." (PMID 39518891, 2024). "In addition, other studies have demonstrated that RORα can bind selectively to promoters of other key tumor suppressor genes." (PMID 39518891, 2024). "Moreover, circGSK3B has been shown to interact with EZH2, impeding its binding to the RORA promoter and resulting in elevated RORA expression, thereby restraining tumor progression." (PMID 39366935, 2024). "Similarly, RORA expression was shown to possess tumor-suppressive functions and to inhibit BC tumor invasion." (PMID 35016723, 2022). "RORα acts as a tumour suppressor in prostate cancer and breast cancer." (PMID 36316442, 2022). "Moreover, using bioinformatics analysis, we probed the function of TIMELESS and RORA in multiple aspects, especially in tumor immune regulation and TIMELESS in lipid metabolism." (PMID 35078435, 2022).